PPY (pancreatic polypeptide)
Diseases named in the same sentence as PPY in open-access papers (continued):
Sharing a sentence is not in itself a finding about the gene and the disease.
malnutrition (1 paper, 2018). Inadequate nutrition resulting from poor diet, malabsorption, or abnormal nutrient distribution. "Although poor appetite is probably a major cause of malnutrition, it is mediated by a variety of factors such as age, several peptide hormones released by the gut including; ghrelin, CCK, peptide-YY, glucagon-like peptide 1, oxyntomodulin, and pancreatic polypeptide and many neurotransmitters." (PMID 30165826, 2018).
metastatic tumors (1 paper, 2015). "No cells in the metastatic tumors stained positive for insulin, somatostatin, or pancreatic polypeptide Y." (PMID 26192435, 2015).
pancreatic disease (1 paper, 2017). "Type 3c DM, also known as pancreatogenic diabetes, originates as a consequence of pancreatic disease, secondary to a deficiency in the nutrient-stimulated release of pancreatic polypeptide, which regulates endocrine and exocrine function." (PMID 28272344, 2017).
tumor (22 papers, 2005 to 2025). "IOBR analysis revealed significant positive correlations between PPY expression and multiple immunosuppressive cell populations, including tumor‐associated macrophages (TAMs), myeloid‐derived suppressor cells (MDSCs), M2 macrophages, exhausted T cells, and regulatory T cells (Tregs)." (PMID 40162859, 2025). "The unique ability of PPY to comprehensively activate the iCAF secretory program suggests its fundamental role in shaping the tumor microenvironment." (PMID 40162859, 2025). "None of the selected proteins retained statistical significance in the main validation analysis, but two proteins of particular interest, FGF-21 and PPY, were identified when stratifying analyses by tumor location, stage and time to diagnosis." (PMID 33664295, 2021). "Immunohistochemistry of the primary tumour a year prior revealed focal positivity for serotonin, as well as insulin, glucagon, and pancreatic polypeptide." (PMID 23476666, 2013). "Immunohistochemistry reveals that the tumor is typically keratin-, vimentin-, pancreatic polypeptide-, and chromogranin-positive, with a lesser number of tumors proving to be neuron-specific-enolase (NSE), synaptophysin-, serotonin- and S-100 protein-positive." (PMID 20111612, 2009). "For the 4T1 tumor model, iPpY/Pt was more effective than PpY/Pt in inhibiting tumor growth." (PMID 34145984, 2021). "One study mentioned that pancreatic polypeptide might be useful as a tumor marker for follow-up purposes." (PMID 15967038, 2005). "More importantly, when assessing tumor volume using the in vivo imaging system (IVIS), tumors in the PPY‐overexpression group exhibited larger sizes compared to those in the control group, while the PPY down‐regulated group showed smaller volumes compared to the control group." (PMID 40162859, 2025). "Tumor marker: Non-specific tumor markers include chromogranin A, pancreatic polypeptide, and neuron-specific enolase." (PMID 39211694, 2024). "PanNETs are categorized as non-functional tumours secreting nonspecific peptides like chromogranin A, low quantity of hormones like pancreatic polypeptide and calcitonin and malignant in 50% to 90%, have an indolent behavior and a better prognosis." (PMID 39246612, 2024). "The tumor cells express SYP, CgA, glucagon and often pancreatic polypeptide (PP)." (PMID 36830839, 2023). "In our multi-institutional retrospective study, we found that the typical epithelioid cells of GP exhibited positive immunoreactivity for the progesterone receptor and pancreatic polypeptide, whereas tumor cells of NET G1 were negative for both markers." (PMID 28096810, 2016). "In our examination of 12 cases of duodenal GP, we found that epithelioid cells of GP exhibited positive reactivity for progesterone receptor and pancreatic polypeptide, whereas tumor cells of NET G1 were completely negative reactivity for both." (PMID 25886293, 2015). "No tumors predominantly expressed insulin, pancreatic polypeptide, or somatostatin, although some harbored focal aggregates of tumor cells expressing one of those hormones." (PMID 21853126, 2011). "Immunohistyochemically, tumor cells were positive for cytokeratin, synaptophysin, neuron-specific enolase, and CD56; they were negative for chromogranin, gastrin, glucagon, somatostatin, pancreatic polypeptide, and vasoactive intestinal polypeptide." (PMID 27990210, 2009).
cancer (5 papers, 2013 to 2025). A tumor composed of atypical neoplastic, often pleomorphic cells that invade other tissues. "Upregulating PPY expression in cancer cells was found to increase the expression of iCAF markers in human and murine CAFs and the proportion of iCAFs, accompanied by decreased expression of myCAF markers and myCAF proportion." (PMID 40162859, 2025). "Conversely, downregulating PPY expression in cancer cells resulted in a decrease in the proportion of iCAFs and their expression of iCAF markers, accompanied by an increased proportion of myCAFs and expression of myCAF markers." (PMID 40162859, 2025). "The results showed significantly higher expression levels of PPY in cancer tissues compared to adjacent normal tissues, which were negatively correlated with patient survival prognosis." (PMID 40162859, 2025). "In this study, single‐cell RNA sequencing analysis is performed to screen for cancer cells‐secreted proteins associated with iCAF induction, and PPY (pancreatic polypeptide) is validated as a potent inducer." (PMID 40162859, 2025). "Conversely, CAFs treated with supernatants from cancer cells with reduced PPY expression or adding PPY antibody to the co‐culture system exhibited an attenuated ability to promote M2 polarization in these macrophages." (PMID 40162859, 2025). "Conversely, when cancer cells with reduced PPY expression were co‐incubated with CAFs, the expression of NF‐κB2 markers in CAFs was downregulated." (PMID 40162859, 2025). "Currently available data on the involvement of neuropeptide Y (NPY), peptide YY (PYY), and pancreatic polypeptide (PP) and their receptors (YRs) in cancer are updated." (PMID 37373115, 2023). "By combining PD‐1 mAb treatment with PPY downregulation, it is possible to enhance the infiltration of functional CD8+ T cells within the TME, thereby inhibiting cancer development and prolonging survival in the PDAC model." (PMID 40162859, 2025). "When PanIN samples were compared to PDACs, the most commonly up-regulated genes in the cancers were POSTN, COL1A2, SULF1, FN1, IGHM, VCAN and XIST, and these down-regulated were PGC and PPY." (PMID 23372777, 2013).
PPY also shares sentences with these, for which no sentence is quoted: Impaired glucose tolerance (3 papers); Alzheimer disease (2); colon cancer (2); Hypercalcemia (2); metabolic disease (2); schizophrenia (2); somatostatinoma (2); Abdominal obesity (1); asthma (1); bacterial meningitis (1); basal cell carcinoma (1); bladder cancer (1); Brain atrophy (1); carcinoid syndrome (1); celiac disease (1); chronic pancreatitis (1); cognitive decline (1); depression (1); dyspepsia (1); gastroesophageal reflux disease (1); Hyperglycemia (1); metastatic cancer (1); migraine disorder (1); neuralgia (1); peripheral neuropathy (1); Sensory neuropathy (1).